CAV1 (caveolin 1)
Diseases named in the same sentence as CAV1 in open-access papers (continued):
Sharing a sentence is not in itself a finding about the gene and the disease.
metastatic tumors (20 papers, 2005 to 2025). "Compared with primary tumors, the levels of Ago2-bound CAV1 were considerably higher in paired metastatic tumors in 90% of the patients, indicating that metastatic tumors are associated with increased Ago2/CAV1 interaction." (PMID 38649663, 2024). "Up-regulation of Cav1 in some primary tumour cells has been reported to be associated with metastatic disease progression." (PMID 23521716, 2013). "We also analyzed the levels of coprecipitated CAV1 by anti-Ago2 antibodies, normalized to the levels of precipitated Ago2, in primary tumors and paired metastatic tumors in the lymph nodes (M) of each patient." (PMID 38649663, 2024). "A direct interaction between Ago2 and CAV1, mediated by the positive charge of Ago2 K212, increases the complexity of miRNA actions and modulates exosomal cargo sorting of metastatic tumors." (PMID 38649663, 2024). "When we analyzed separately the outcomes of patients with locally advanced PDAC and with metastatic disease, the prognostic role of tumoral Cav-1 was confirmed in both settings." (PMID 34590611, 2021). "Fatty acid uptake-related genes, such as caveolin-1 and CD36, are abundantly present in metastatic tumors and have been associated with EMT in multiple cancer." (PMID 32327627, 2020). "Fatty acid uptake-related genes, such as caveolin-1 (CAV1) and CD36, are abundantly present in metastatic tumors and have been associated with EMT in multiple cancers." (PMID 31822964, 2020). "We also found significant concordance in the expression of Cav-1 and pERK-1/2, either alone or combined, between matched primary and metastatic tumours." (PMID 24119769, 2013). "We have previously shown that increased caveolin-1 serves as a statistically significant indicator of subsequent metastatic disease and poor clinical outcome in patients who initially presented with localised RCC." (PMID 18283322, 2008). "The same was true for tissue samples: normal prostate expressed very low levels of caveolin-1, which was up-regulated in primary tumours and further up-regulated in metastatic tumours." (PMID 18949068, 2007). "Two recent studies have demonstrated a biphasic expression of cav-1 in primary vs. metastatic tumors." (PMID 15969750, 2005). "Given the role of RhoC in cellular migration and its prevalence in metastatic tumors, it was a logical choice to examine in relationship to cav-1." (PMID 15969750, 2005). "Therefore, the release of specific miRNAs (e.g., miR-3613-3p) from metastatic tumors in circulation through EVs, facilitated by the increased Ago2/CAV1 interaction in metastatic tumors, can be used as a biomarker of tumor progression." (PMID 38649663, 2024). "In this study, the cellular FA uptake genes CAV1 and CD36 were found to be amplified in metastatic tumors, their gene expression patterns were consistently associated with EMT scores across multiple cancer types and emerged as members of the predictive gene signature." (PMID 26725848, 2016). "In 14 of 16 pairs Cav-1 expression was concordant (88%) between primary and metastatic tumours." (PMID 24119769, 2013). "Since Ago2/CAV1 interaction increases with human carcinoma progression and metastasis, we also investigated whether EV-mediated miR-3613-3p release increases in the plasma of patients with metastatic tumors." (PMID 38649663, 2024). "These contradictory results could be due to the complex biologic behavior of Cav-1 protein, which depends on the location of this molecule and interaction of signaling pathways, which might mean the different roles between primary and metastatic tumors." (PMID 28828003, 2017). "In conclusion, the coexpression of caveolin-1 and activated components of the AKT/mTOR pathway represents a ‘linked molecular signature’ that identifies patients with localised RCC that are at high risk of developing metastatic disease that warrants greater postoperative surveillance." (PMID 18283322, 2008).
metastatic tumors (continued). "Genetic alterations in metabolic genes associated with metastatic progression analyzed, revealed that genes involved in cellular fatty acid uptake (CAV1, CD36) and de novo lipogenesis (PPARA, PPARD, MLXIPL) were specifically amplified at higher frequencies in metastatic tumors." (PMID 28798698, 2017). "Correlation between primary tumoral, stromal, and metastatic tumoral Cav-1 expression was not identified (primary tumor versus metastatic tumor, P = 1.000; primary stroma versus metastatic tumor, P = 0.522)." (PMID 28828003, 2017). "However, 6 genes were amplified at significantly higher frequencies in metastatic tumors: SCO2 (p = 1.1 × 10−9), MLXIPL (p = 2.1 × 10−4), PPARA (p = 1.2 × 10−10), PPARD (p = 4 × 10−15), CAV1 (p = 3.4 × 10−4) and CD36 (p = 3.5 × 10−4)." (PMID 26725848, 2016). "However, genes involved in cellular FA uptake (CAV1, CD36) and de novo lipogenesis (PPARA, PPARD, MLXIPL) were specifically amplified at higher frequencies in metastatic tumors." (PMID 26725848, 2016). "To further support the implication of Cav-1/ACC1/FASN signaling in the progression of PCa we performed Cav-1, ACC1 and FASN immunostaining in normal prostate tissues, primary untreated and ADT treated PCa and metastatic disease." (PMID 27331874, 2016). "Using a model of spontaneous breast metastasis, caveolin-1 appeared to be expressed in low and non-metastatic primary tumors and to be expressed at much lower levels in highly metastatic tumors." (PMID 25594072, 2014). "Furthermore, the appearance of CAV1 and CD36 across all the cancer types in this study clearly supports the role of elevated cellular FA uptake and accumulation in the progression and maintenance of metastatic tumors." (PMID 26725848, 2016). "Thus, in metastatic tumors, the role of caveolin-1 as a tumor suppressor is absent, allowing the tumor to spread." (PMID 25594072, 2014).
osteosarcoma (20 papers, 2008 to 2025). A usually aggressive malignant bone-forming mesenchymal neoplasm, predominantly affecting adolescents and young adults. "A previous study found that abnormal expression of CAV1 is associated with the degree of malignancy of osteosarcoma cells, with CAV1 downregulation in highly malignant cells." (PMID 33886809, 2021). "Although only a limited number of osteosarcoma samples were analyzed, we found that CAV1 mRNA was significantly downregulated in the osteosarcoma tissues compared to adjacent healthy tissues (P=0.0009)." (PMID 33886809, 2021). "In osteosarcoma, CAV1 was found to be significantly decreased in high-grade osteosarcoma compared to normal controls." (PMID 33886809, 2021). "Reportedly, cav-1 overexpression prevents autophagy in human osteosarcoma cells and cav-1 deletion increases basal autophagy in the vascular endothelium." (PMID 34321069, 2021). "Overexpression of Caveolin-1 has been shown to reduce paclitaxel resistance of osteosarcoma cells via weakening autophagy, and the AKT/JNK pathway is an effective regulator for autophagy." (PMID 33937013, 2021). "Overall, our study confirmed that miR-629-5p promoted osteosarcoma proliferation and migration by directly inhibiting CAV1." (PMID 33886809, 2021). "In this study, we found that CAV1 overexpression repressed the malignant phenotype in osteosarcoma cells." (PMID 33886809, 2021). "Together, these data provide direct evidences that CAV-1 vesicles interact with actin network in human osteosarcoma cells." (PMID 33928090, 2021). "Our results were similar to a study that showed that CAV1 inhibited osteosarcoma cell (Saos-2 cell line) proliferation and invasion by upregulating the calcium sensing-receptor CaSR." (PMID 33886809, 2021). "In this study, we demonstrated that miR-629-5p and CAV1 played crucial roles in osteosarcoma development." (PMID 33886809, 2021). "In another study, high metastatic mouse osteosarcoma FBJ-S1 cells were found to have lower expression of CAV1 compared to low metastatic FBJ-LL cells." (PMID 33886809, 2021). "CAV1 expression, which was negatively correlated with miR-629-5p expression, was found to be downregulated in osteosarcoma tissue samples." (PMID 33886809, 2021). "Our results showed that an increase in miR-629-5p promoted the malignant phenotype of osteosarcoma cell lines by directly suppressing CAV1." (PMID 33886809, 2021). "Conversely, overexpression of Cav-1 in osteosarcoma cell lines brought reduced malignancy with inhibited anchorage-independent growth, migration, and invasion." (PMID 28546853, 2017). "CAV1 has been shown to act as an oncosuppressor in human osteosarcoma; its down-regulation is part of osteoblast transformation and osteosarcoma progression." (PMID 21471610, 2011). "In the study the authors did a survey of 6-year follow-up that indicated a better overall survival for osteosarcoma expressing a level of CAV1 similar to osteoblasts." (PMID 21471610, 2011). "In vitro, osteosarcoma cell lines forced to overexpress CAV1 showed reduced malignancy with inhibited anchorage-independent growth, migration and invasion." (PMID 21471610, 2011). "The expression of Cav-1 is related to the drug resistance of human osteosarcoma." (PMID 41030451, 2025). "In the Taxol-resistant osteosarcoma cells, Cav-1 is downregulated and autophagy is activated." (PMID 41030451, 2025). "But whether Cav-1 can achieve clinical translation in drug-resistant patients with osteosarcoma still requires more preclinical experimental support." (PMID 41030451, 2025). "In addition, CAV1 was shown to reduce paclitaxel resistance in osteosarcoma cells by attenuating PI3K-Akt-JNK-dependent autophagy." (PMID 33886809, 2021). "We also analyzed the expression of CAV1 mRNA in osteosarcoma cell lines." (PMID 33886809, 2021). "The results showed that CAV1 was significantly downregulated in osteosarcoma cell lines (P<0.05)." (PMID 33886809, 2021).
osteosarcoma (continued). "Bioinformatics analysis revealed that low expression of CAV1 was a key regulator of osteosarcoma and may be the target gene of miR-629-5p." (PMID 33886809, 2021). "In addition, CAV1 was downregulated in osteosarcoma tissues and cell lines, and its overexpression reduced osteosarcoma cell proliferation and migration." (PMID 33886809, 2021). "Taken together, these results indicate that CAV1 acts as a tumor suppressor in osteosarcoma." (PMID 33886809, 2021). "In this study, we found that CAV1 was downregulated in osteosarcoma tissues." (PMID 33886809, 2021). "In osteosarcoma, Cav-1 downregulation could unleash c-Src and Met signaling, enabling osteosarcoma cells to invade neighboring tissues." (PMID 28546853, 2017). "In contrast, in a recent immunohistochemical study of 61 xenotransplanted osteosarcoma tumors it was shown that CAV1 showed immunoreactivity in the majority of the tumors with no significant variation among the subtypes or subsequent passages; even in the majority of the metastatic cases." (PMID 21471610, 2011). "Moreover, the majority of primary osteosarcoma showed significantly lower levels of CAV1 than normal osteoblasts suggesting its role as an oncosuppressor." (PMID 21471610, 2011). "In vivo, CAV1 overexpression abrogated the metastatic ability of osteosarcoma cells." (PMID 21471610, 2011). "Moreover, our data showed that an increase in CAV1 level led to a decline in osteosarcoma cell proliferation and migration, which could be rescued by miR-629-5p upregulation." (PMID 33886809, 2021). "Osteosarcoma tissue core from the cTMA was chosen to validate the presence of the CAF markers: α-SMA, integrin α11, FAP, collagen-1, FSP-1, CD140β, caveolin-1 and CD90." (PMID 38803925, 2024). "This study aimed to explore the role of miR-629-5p and its target gene, caveolin 1 (CAV1), in osteosarcoma development." (PMID 33886809, 2021). "So far, the research on Cav-1 and autophagy in diseases of blood system is still very limited, and the relevant content is only mentioned in two articles on chronic myeloid leukemia (CML) and osteosarcoma." (PMID 41030451, 2025). "Similarly comparable staining of FSP-1, CD140β and caveolin-1 was observed between IMC and IHC in the osteosarcoma core of the cTMA." (PMID 38803925, 2024). "Another study reported the negative effect of CAV1 on osteosarcoma cells by reducing cell proliferation and invasion." (PMID 33886809, 2021). "As the relationship between CAV1 and miR-629-5p in osteosarcoma has not been examined previously, this study aimed to identify the roles of miR-629-5p and its potential target gene, CAV1, in osteosarcoma cell phenotypes." (PMID 33886809, 2021). "To investigate whether the YAP/TAZ-TEAD transcriptional complex is essential for the expression of CAV1 and CAVIN1 in other cells, we chose the osteosarcoma cell line U2OS." (PMID 30595521, 2019). "CAV1, which is downregulated in schwannomas, has been found to inhibit MET signaling in osteosarcoma transformation, which suggests that if this mechanism is analogous, CAV1 downregulation could trigger MET signaling in schwannomas." (PMID 23354516, 2013). "Moreover, we found that cell lines of other tumor histotypes (osteosarcoma and CRC) secreted exosomes expressing variable levels of CD63 and Cav1, in line with the reported cellular expression of Cav1 in these cancers." (PMID 19381331, 2009). "It has been reported that sclareol, a plant diterpene, inhibits the growth of osteosarcoma tumor cells MG63 (IC50 of 65.2 μM); inhibits cell proliferation in leukemic, breast, and HeLa cancer cells; induces apoptosis via regulation of the caveolin-1 (Cav-1) protein P13K, STAT5, and NF-kB pathways." (PMID 35214995, 2022). "In addition, a negative correlation was identified between miR-629-5p and CAV1 expression in osteosarcoma tissues (P<0.001)." (PMID 33886809, 2021).
osteosarcoma (continued). "Modulating the Cav-1/autophagy axis (e.g. inhibiting Cav-1 to enhance radiotherapy sensitivity in NSCLC, or overexpressing Cav-1 to inhibit autophagy and reverse paclitaxel resistance in osteosarcoma) may represent novel strategies to overcome therapeutic resistance in tumors." (PMID 41030451, 2025).
myocardial infarction (19 papers, 2008 to 2025). Gross necrosis of the myocardium, as a result of interruption of the blood supply to the area, as in coronary thrombosis. "The mechanisms underlying these effects in caveolin-1-knockout mice subjected to myocardial infarction are the reduced density of β-adrenergic receptors at the plasma membrane and diminished cAMP levels and PKA phosphorylation." (PMID 32257548, 2020). "The deletion of the gene encoding Cav-1 leads to adverse cardiac remodeling following myocardial infarction (MI)." (PMID 28970796, 2017). "Recent genome wide association reports have shown for that Cav-1 SNPs are associated with stroke disease and that the Cav-1 G14713A elevates risk of coronary artery disease and myocardial infarction." (PMID 28346478, 2017). "In a rat myocardial infarction model, the high cholesterol diet-induced complications such as increased lipid levels, Cav-1 expression and Cav-1/eNOS association, as well as reductions in myocardial functions, can be normalized with resveratrol therapy." (PMID 25302702, 2014). "Interestingly, we found that Cav-1 deficiency significantly amplified the size of myocardial infarction areas, alongside the deteriorated cardiac function in vivo." (PMID 39991756, 2025). "We investigated the effect of Cav1 and caveolae loss in cardiac regeneration using the cryoinjury model, as it mimics the mammalian myocardial infarction in formation of necrotic myocardium and scar tissue, which in the zebrafish gradually resolves leading to complete tissue regeneration at 90 dpci." (PMID 32733088, 2020). "Interestingly, in the MCT and myocardial infarction models of PH, in addition to loss of caveolin-1, caveolin-2 loss occurs, and the rescue of caveolin-1 attenuates PH and also restores caveolin-2 expression." (PMID 21660237, 2011). "Cav-1 was dissociated from caveolae to the cytosol in rat hearts after myocardial infarction, which increased cytosolic Cav-1/endothelial NOS (eNOS) complexes, and subsequently, decreased the production of NO, a molecule to limit deleterious effects of ROS." (PMID 40041164, 2025). "Loss of endothelial caveolin-1 has been reported in clinical and experimental forms such as monocrotaline (MCT) and myocardial infarction models of PH." (PMID 21660237, 2011). "Clinically, a down-regulation of Cav-1 was observed in plaques obtained from men, patients with a history of myocardial infarction and restenotic lesions." (PMID 18596970, 2008). "Besides, myocardial infarction models demonstrate that Cav-1 reduction correlates with increased M2 macrophage infiltration within infarct zones." (PMID 40430042, 2025). "Also, Cav1 deletion exacerbated cardiac interstitial fibrosis in mice by promoting M2 macrophage activation after myocardial infarction." (PMID 34434195, 2021). "Moreover, Cav1 deletion promotes a multitude of maladaptive repair processes after myocardial infarction, including increased M2 macrophage infiltration and dysregulated M1/M2 balance." (PMID 34434195, 2021). "Despite similar infarct sizes, caveolin-1-knockout mice subjected to myocardial infarction showed a decreased left ventricular ejection fraction and fractional shortening, as well as increased left-ventricular diastolic pressures, as compared to those in control mice." (PMID 32257548, 2020). "Similarly, Cav1 deletion exacerbates cardiac interstitial fibrosis by promoting M2 macrophage activation in mice after myocardial infarction." (PMID 29891777, 2018). "In addition, patients with a history of myocardial infarction had lower levels of Cav-1, supporting the relation between local plaque levels of Cav-1 and vulnerability for vascular events." (PMID 18596970, 2008). "Patients with a history of myocardial infarction had lower levels of Cav-1 than patients with no such history (13.3 vs. 20.5; p = 0.04)." (PMID 18596970, 2008). "However, the role of Cav-1 in myocardial infarction (MI) has not been fully elucidated." (PMID 39991756, 2025).
type 2 diabetes (18 papers, 2014 to 2025). "Caveolin-1 (cav-1), the principal structural and signalling protein of caveolae, is implicated in various signalling events, including apoptotic cell death in type 2 diabetes." (PMID 31728004, 2019). "Cav-1 depletion has been extensively implicated in the pathogenesis of type 2 diabetes." (PMID 41280311, 2025). "Based on our study using the GK rat as a type 2 diabetic model, we observed a significant increase in the proportion of CaV1.2E9* channel and a decrease in CaV1.2E33 channel." (PMID 38575795, 2024). "Compared with healthy aging, endothelial-enriched levels of Cav1 are reduced in type 2 diabetes and negatively correlated with Aβ levels." (PMID 37174641, 2023). "Compared with the NC group, type 2 diabetic mice were presented with reduced Caveolin-1 (green) and GLUT4 (red) fluorescence intensity (fluorescence intensity of Caveolin-1: 11.46 ± 3.29 vs. 6.74 ± 1.35, GLUT4: 9.915 ± 1.29 vs. 5.87 ± 0.98)." (PMID 34917687, 2021). "In this study, we used lentivirus to silence Cav-1 in type 2 diabetic mice and investigated the effect of Cav-1 depletion on insulin sensitivity, PI3K p110 expression, and AKT activation after glargine treatment." (PMID 34917687, 2021). "Combined AT and RT is an effective way to improve EPC function through upregulation of caveolin-1 in mice with type 2 diabetes." (PMID 31900223, 2020). "Consistent with these two studies, our study indicated that AT+RT enhanced EPC function by upregulating caveolin-1 in mice with type 2 diabetes." (PMID 31900223, 2020). "Some recent reports have already related caveolin-1 to cognitive impairment, and more interestingly, that caveoin-1 might provide the potential link for type 2 diabetes and AD co-occurrence in pathological aging." (PMID 35600079, 2022). "However, it is unknown if there is either an increase or decrease in Cav-1 expression in diabesity, as seen in type II diabetes." (PMID 33995826, 2021).